OXCT2 (3-oxoacid CoA-transferase 2)
Description:
Key enzyme for ketone body catabolism. Transfers the CoA moiety from succinate to acetoacetate. Formation of the enzyme-CoA intermediate proceeds via an unstable anhydride species formed between the carboxylate groups of the enzyme and substrate (By similarity).
Synonyms: SCOT-t; FKSG25; FLJ00030; SCOTT
Tractability: No criterion of Open Targets' tractability assessment is met for any kind of drug.
Gene: Protein-coding gene on chromosome 1 (39,769,523 to 39,771,348, reverse strand). Ensembl gene ENSG00000198754.
Subcellular location: Mitochondrion
Pathways (Reactome):
Metabolism: Utilization of Ketone Bodies
Gene Ontology:
Molecular function: protein binding; succinyl-CoA:3-oxo-acid CoA-transferase activity; CoA-transferase activity
Biological process: ketone body catabolic process
Cellular component: mitochondrion; motile cilium; mitochondrial matrix
Genetic constraint (gnomAD): Missense variants: 239 observed, 363.62 expected, observed/expected ratio (o/e) 0.66, 90% interval 0.59 to 0.73. Synonymous variants: 81 observed, 145.8 expected, observed/expected ratio (o/e) 0.56, 90% interval 0.46 to 0.67.
Homologues: Orthologues: guinea pig OXCT2 (78% identical), mouse Oxct2a (75% identical), mouse Oxct2b (75% identical), rat Oxct2a (74% identical), rat Oxct2b (74% identical), tropical clawed frog oxct1 (68% identical), zebrafish oxct1a (68% identical), zebrafish oxct1b (66% identical), Drosophila melanogaster SCOT (57% identical), Caenorhabditis elegans C05C10.3 (55% identical). Paralogues in human: OXCT1 (74% identical).
Diseases named in the same sentence as OXCT2 in open-access papers:
OXCT2 is named in the same sentence as 4 diseases in open-access papers, as found by Europe PMC text mining. Sharing a sentence is not in itself a finding about the gene and the disease. The quoted sentences say what the papers report.
acute tonsillitis (1 paper, 2021). An acute inflammation of the tonsils caused by viruses or bacteria. "Nearly half of the acute tonsillitis cases (452/1000) from the lowest PB risk group were predicted to be OXCT2 missense mutation carriers, which was a nearly threefold increase relative to the highest PB risk group." (PMID 34285202, 2021).
OXCT2 also shares sentences with these, for which no sentence is quoted: Infertility (1 paper); lung carcinoma (1); male infertility (1).